SLC1A4 (solute carrier family 1 member 4)
Diseases named in the same sentence as SLC1A4 in open-access papers (continued):
Sharing a sentence is not in itself a finding about the gene and the disease.
dilated cardiomyopathy (1 paper, 2022). Cardiomyopathy which is characterized by dilation and contractile dysfunction of the left and right ventricles. "Besides, we also found that CEBPG was closely related to the ‘Regulation of actin cytoskeleton’ (also enriched in SLC1A4, STMN1 and CBS), ‘Vascular smooth muscle contraction’, ‘Dilated cardiomyopathy’, ‘Relaxin signalling pathway’, ‘Cardiac muscle contraction’ and ‘Hypertrophic cardiomyopathy’." (PMID 35152560, 2022).
mastitis (1 paper, 2025). Inflammation of breast tissue during lactation or postpartum due to an obstructed duct or infection. "The three prioritized genes for both Trait_GWAS and EBV_GWAS datasets (PHGDH, SLC1A4, and CSN3) play relevant roles in biological processes associated with milk production, cheese production, and resistance to mastitis." (PMID 41306553, 2025).
metastatic melanoma (1 paper, 2023). A melanoma that has spread from its primary site to another anatomic site. "As for the immunomodulatory mechanism of SNTB2, SLC1A4, LAMP3 and CCDC69 in metastatic melanoma or macrophages, it was not specifically elucidated, though it is still a promising research direction." (PMID 37762054, 2023).
metastatic tumors (1 paper, 2024). "The expressions of both cystine transporters (SLC7A11, SLC3A2) and cysteine transporters (SLC1A4, SLC1A5) were significantly upregulated in CRC compared with paired non-tumor tissues, but were similar in primary tumors and metastatic tumors." (PMID 39079386, 2024).
Neurodevelopmental delay (1 paper, 2023). "The presented cases expand the genetic and clinical spectrum of ASCT1 deficiency and support the importance of including SLC1A4 gene screening in infants with unexplained global neurodevelopmental delay regardless of ethnicity." (PMID 37502193, 2023).
non-small cell lung carcinoma (1 paper, 2024). A group of at least three distinct histological types of lung cancer, including non-small cell squamous cell carcinoma, adenocarcinoma, and large cell carcinoma. "In contrast, it showed that SLC1A4 expression is downregulated in non-small cell lung cancer cells (NSCLC), while SLC38A1, SLC1A5, SLC7A5, and SLC7A11 were upregulated." (PMID 38705513, 2024).
ovarian carcinoma (1 paper, 2022). A malignant neoplasm originating from the surface ovarian epithelium. "In addition, through the literature review, we found that except CYBB, VDAC2, IDH1, MT1G, SLC1A4, PCK2, SLC3A2, the prognostic value of other FRGs in ovarian cancer has been reported, which provided a possibility for constructing a prognostic model." (PMID 36386203, 2022).
tumor (19 papers, 2020 to 2026). "SLC1A4 expression was also significantly associated with immune subtype, stroma score and tumor stem cell RNAs score." (PMID 33777811, 2021). "We next analyzed the association between SLC1A4 and tumor microenvironment, tumor stem cell score in HCC." (PMID 33777811, 2021). "And SLC1A4 was significantly associated with the stroma score and tumor stem cell RNAs score." (PMID 33777811, 2021). "Through conducting qRT-PCR, we verified the high expression of SLC1A4 in tumor tissues of clinical HCC samples." (PMID 39949345, 2025). "Meanwhile, the protein level of SLC1A4 in tumor tissues of HCC examined by Western blot was also uncovered to be generally higher than that in adjacent tissues." (PMID 39949345, 2025). "Through analyzing HCC data in the TCGA database, we revealed that the transcript level of SLC1A4 in tumor tissues of HCC was significantly higher than that in adjacent tissues." (PMID 39949345, 2025). "Through analyzing the TCGA database and clinical tissue specimens, this study uncovered the high expression of SLC1A4 in tumor tissues of HCC." (PMID 39949345, 2025). "In this study, an SLC transporter named SLC1A4 was found to be highly expressed in tumor tissues of HCC, and a high level of SLC1A4 was tightly associated with the poor prognosis of HCC." (PMID 39949345, 2025). "Increased serine synthesis or uptake of exogenous serine from the tumor environment by solute carrier family 1 member 4 (SLC1A4) and solute carrier family 7 member 5 (SLC7A5) is necessary for therapy resistance in many cancers." (PMID 40667288, 2025). "SkII treatment significantly reduced SLC1A4 levels in both mouse tumor tissues and human GC organoids." (PMID 40971730, 2025). "The pancancer analysis showed that SLC1A4 mRNA was remarkably elevated in most tumor tissues, including BRCA, COAD, DLBC, ESCA, and so on." (PMID 33777811, 2021). "According to these results, SLC1A4 played a crucial role in immune activities in the tumor microenvironment." (PMID 33777811, 2021). "Importantly, the STAT3/SLC1A4 axis regulated cysteine uptake, tumor killing by T cells and the efficacy of anti-PD-L1 immunotherapy." (PMID 41604939, 2026). "Furthermore, SLC1A4 was highly expressed in tumor tissues, and SkII reduced SLC1A4 protein levels in a dose‐dependent manner." (PMID 40971730, 2025). "Interestingly, competing endogenous RNAs (ceRNAs) network analysis demonstrated a correlation between ZFP36, TGFBR1, MYB, SP1, and Solute Carrier Family 1 Member 4 (SLC1A4) ferroptosis-related genes and ceRNA processes affecting the tumor microenvironment." (PMID 37132605, 2024). "However, the potential correlation of SLC1A4 expression and tumor immune infiltrations need to be further approved by experimental data." (PMID 33777811, 2021). "Moreover, the expression level of SLC1A4 was strongly associated with tumor size and TNM stage, suggesting that SLC1A4 may have contributed to the progression of GC (P<0.05)." (PMID 40971730, 2025). "So, we speculated the important role of SLC1A4 in HCC by regulating tumor microenvironment." (PMID 33777811, 2021). "The results showed that PSAT1 and PSPH were consistently upregulated in tumour tissues in five GEO datasets, while PHGDH, SLC1A4 and SLC38A5 were upregulated in four datasets." (PMID 40660426, 2025). "While the exact transporters involved in serine uptake within tumours remain incompletely defined, members of the solute carrier (SLC) superfamily, such as SLC1A4 (ASCT1), SLC1A5 (ASCT2), SLC7A10, SLC38A2, SLC38A4 and SLC38A5, have been implicated." (PMID 40660426, 2025). "Critically, PHGDH, PSAT1, PSPH, SLC1A4, SLC1A5 and SLC38A2 show robust co‐expression patterns in both TCGA tumour samples and CCLE cancer cell lines, suggesting coregulated functionality." (PMID 40660426, 2025). "Among these, SLC1A4 and SLC1A5 are key transporters of neutral amino acids and are frequently upregulated in tumours, correlating with poor prognosis." (PMID 40660426, 2025).
tumor (continued). "In 50 paired tumors and adjacent non-tumor tissues from TCGA COREAD database, 27 of 50 (54 %) CRC samples showed upregulation of SLC1A4, SLC1A5, SLC7A11 and SLC3A2 simultaneously, and 17 of 50 (34 %) CRC samples showed upregulation of three transporter genes." (PMID 39079386, 2024). "NQO1, SLC1A4, and NOS2 were identified as potential genes in HB and found to be significantly upregulated in tumor samples." (PMID 37795447, 2023). "SLC1A4 and SLC38A2 (alanine transporter) and SLC1A5 (ASCT2-glutamine transporter) enhance PDAC tumor growth by importing essential amino acids and therefore represent additional potential therapeutic targets." (PMID 33198082, 2020). "Regarding methylation levels, cg09596674 (LRRC2) exhibited higher methylation in both the TCGA and in-house LUAD tumor tissues compared to adjacent non-tumor tissues, while cg19220282 (SLC1A4) showed consistently lower methylation in LUAD tumor tissues." (PMID 41249120, 2025). "Notably, at the protein levels, SLC1A4 and SLC1A5 were highly expressed in most CRC tumors, and SLC7A11 was highly expressed in more than half of tumor samples." (PMID 39079386, 2024). "Furthermore, SLC1A4/SLC1A5, the main transporters of serine, are upregulated in serine-dependent tumor cells." (PMID 33269112, 2020). "However, whether AKT or β-catenin may function as transcription factors of c-Myc and EpCAM regulated by SLC1A4 is still unclear, and the potential regulation of SLC1A4 in tumor microenvironment represented by cancer immunity is not referred to in this study." (PMID 39949345, 2025). "For SLC1A4, its expression was significantly higher in LUAD tumor tissues compared to adjacent non-tumor tissues in the TCGA dataset, validation in the GSE31210 dataset confirmed the TCGA findings." (PMID 41249120, 2025).
cancer (17 papers, 2016 to 2025). A tumor composed of atypical neoplastic, often pleomorphic cells that invade other tissues. "As for malignant tumors, the differentially expressed SLC1A4 has been identified to be a prognostic factor in breast cancer." (PMID 39949345, 2025). "Decreased level of circulating amino acids is linked to increased uptake by cancer cells due to overexpression of amino acid transporters, including SLC1A5 (Gln uptake), SLC1A4 (Ser uptake), SLC7A5 (Leu, Ile, and Val uptake), or SLC7A1 (Arg uptake)." (PMID 38646441, 2024). "It was found that SLC1A4 overexpression is a powerful prognostic biomarker and is accompanied by cancer cell cycle progression, metabolism, oncogenic pathways, proliferation, and migration, while it mediates apoptosis suppression." (PMID 38705513, 2024). "The series of hydroxyproline analogs identified here represent promising new agents to pharmacologically modulate SLC1A4 and SLC1A5 amino acid exchangers which are implicated in numerous pathophysiological processes such as cancer and neurological diseases." (PMID 38792190, 2024). "It was also found that SLC1A4 promotes rapid proliferation, invasion, and metastasis by regulating metabolic reprogramming, and also increases cancer stem cell abilities." (PMID 38705513, 2024). "The co-expressed genes analysis and GSEA analysis showed that SLC1A4 was related to cell cycle, metabolism, cancer-related pathway." (PMID 33777811, 2021). "The uptake of extracellular serine and glycine is required for migration, and motility of cancer cells can be effectively impaired by using inhibitors of the serine/glycine transporters SLC1A4/SLC1A5 and GlyT1, which are involved in this process." (PMID 33243973, 2020). "Moreover, the number and size of cancer stem cell spheres formed by Huh7 cells were decreased with the knockdown of SLC1A4." (PMID 39949345, 2025). "The results of integrative bioinformatics and functional profiling indicated that SLC1A4 may involve in regulating cancer phenotypes, immune regulation, and drug resistance in HCC, but the regulatory role and mechanism of SLC1A4 in HCC is still obscure." (PMID 39949345, 2025). "Interestingly, the decreased cancer stemness triggered by the downregulation of SLC1A4 was enhanced and reinforced by the introduction of exogenous AKT again." (PMID 39949345, 2025). "Importantly, cells were shown high sensitivity toward anti-cancer therapies when the expression level of SLC1A4 is low." (PMID 38705513, 2024). "ASCT1 (SLC1A4) and ASCT2 (SLC1A5) transporters exhibited high expression in most cancer cell lines, with the exceptions of ASCT1 and ASCT2 that were virtually undetectable in MiaPaCa-2 or Capan-2, respectively." (PMID 33801101, 2021). "Other genes whose protein products have evidence of function in cancer include RCN3, RRBP1, PDLIM3 and SLC1A4." (PMID 27689402, 2016). "We postulate that other AA transporters, such as ASCT1 (SLC1A4) and ASCT2 (SLC1A5), might be more important for serine uptake in MCF7 cancer cells." (PMID 31152137, 2019).
neurological disorders (2 papers, 2023 to 2024). "Underscoring the significance of SLC1A4 within the nervous system, mutations in the corresponding human gene have been linked to neurological disorders, including cognitive and developmental impairment." (PMID 38792190, 2024).
brain disorder (1 paper, 2025). A disease affecting the brain or part of the brain. "These inhibitors pharmacologically modulate transporter function and, if they cross the BBB, could be used to treat AD, TBI, and other brain disorders associated with NMDA-mediated excitotoxicity due to increased SLC1A4-mediated D-serine efflux from inflammatory astrocytes." (PMID 40076728, 2025).
SLC1A4 also shares sentences with these, for which no sentence is quoted: infection (5 papers); developmental delay (4); neurodevelopmental disorder (3); cognitive deficits (2); epilepsy (2); Parkinson disease (2); tetraplegia (2); Anxiety (1); Ataxia (1); atherosclerosis (1); atrial fibrillation (1); breast tumors (1); cataract (1); cognitive decline (1); cone-rod dystrophy (1); depression (1); diabetes (1); Epileptic encephalopathy (1); gout (1); heart failure (1); hypertrophic cardiomyopathy (1); inflammation (1); leukemia (1); limb girdle muscular dystrophy type 2S (1); Menkes disease (1); mitochondrial DNA depletion syndrome (1); mitral valve prolapse (1); Motor Neuron Disease (1); myoclonic epilepsy (1); myotonic dystrophy type 1 (1).
A further 11 diseases each share a sentence with SLC1A4 in 1 paper.